RNU7-87P (RNA, U7 small nuclear 87 pseudogene)
Gene: Small nuclear RNA gene on chromosome 13 (66,630,715 to 66,630,776, reverse strand). Ensembl gene ENSG00000238500.
Homologues: Orthologues: chimpanzee U7 (98% identical), macaque U7 (95% identical). Paralogues in human: RNU7-187P (79% identical), RNU7-70P (79% identical), RNU7-73P (79% identical), RNU7-94P (79% identical), RNU7-20P (77% identical), RNU7-28P (77% identical), RNU7-34P (77% identical), RNU7-37P (77% identical), RNU7-50P (77% identical), RNU7-120P (76% identical), RNU7-130P (76% identical), RNU7-172P (76% identical), and 142 more.